UPF2 (UPF2 regulator of nonsense mediated mRNA decay)
Description:
Involved in nonsense-mediated decay (NMD) of mRNAs containing premature stop codons by associating with the nuclear exon junction complex (EJC). Recruited by UPF3B associated with the EJC core at the cytoplasmic side of the nuclear envelope and the subsequent formation of an UPF1-UPF2-UPF3 surveillance complex (including UPF1 bound to release factors at the stalled ribosome) is believed to activate NMD. In cooperation with UPF3B stimulates both ATPase and RNA helicase activities of UPF1. Binds spliced mRNA.
Synonyms: hUpf2; KIAA1408; RENT2; DKFZP434D222; smg-3
Tractability: PROTAC: ubiquitination databases record sites on it; its protein half-life has been measured.
Gene: Protein-coding gene on chromosome 10 (11,920,020 to 12,043,170, reverse strand). Ensembl gene ENSG00000151461.
Subcellular location: Cytoplasm, perinuclear region; Cytoplasm
Subcellular location (Human Protein Atlas): Cytosol; Cytoplasmic bodies; Primary cilium; Primary cilium tip; Vesicles
Pathways (Reactome):
Developmental Biology: Regulation of expression of SLITs and ROBOs
Metabolism of RNA: Nonsense Mediated Decay (NMD) enhanced by the Exon Junction Complex (EJC)
Gene Ontology:
Molecular function: protein binding; telomeric DNA binding; RNA binding
Biological process: nuclear-transcribed mRNA catabolic process, nonsense-mediated decay; mRNA export from nucleus; negative regulation of nuclear-transcribed mRNA catabolic process, nonsense-mediated decay; positive regulation of nuclear-transcribed mRNA catabolic process, nonsense-mediated decay; RNA surveillance
Cellular component: cytoplasm; cytosol; exon-exon junction complex; nucleus; nonsense-mediated decay complex; perinuclear region of cytoplasm
Genetic constraint (gnomAD): Loss-of-function variants: 13 observed, 130.37 expected, observed/expected ratio (o/e) 0.0997, 90% interval 0.064 to 0.16. The upper end of that interval is the gene's LOEUF score, 0.16, which puts it in group 1 of 6, group 1 being the genes least tolerant of losing a copy. Missense variants: 1,116 observed, 1,517.6 expected, observed/expected ratio (o/e) 0.74, 90% interval 0.7 to 0.77. Synonymous variants: 527 observed, 503.06 expected, observed/expected ratio (o/e) 1.05, 90% interval 0.98 to 1.13.
Homologues: Orthologues: chimpanzee UPF2 (99% identical), macaque UPF2 (99% identical), dog UPF2 (98% identical), pig UPF2 (98% identical), rabbit UPF2 (97% identical), rat Upf2 (97% identical), mouse Upf2 (97% identical), guinea pig UPF2 (95% identical), tropical clawed frog upf2 (87% identical), Drosophila melanogaster Upf2 (36% identical), Caenorhabditis elegans smg-3 (26% identical).
Diseases named in the same sentence as UPF2 in open-access papers:
UPF2 is named in the same sentence as 25 diseases in open-access papers, as found by Europe PMC text mining. Sharing a sentence is not in itself a finding about the gene and the disease. The quoted sentences say what the papers report.
HIV-1 infection (3 papers, 2012 to 2019). The type species of lentivirus and the etiologic agent of acquired immunodeficiency syndrome (AIDS). "Therefore we wanted to determine the potential association of some of the main NMD factors such as Upf1, Upf2, and Upf3 in Staufen1-containing RNPs in the absence or presence of HIV-1 infection." (PMID 23125841, 2012). "During HIV-1 infection, we have previously demonstrated that UPF2 is excluded from HIV-1 RNPs through antagonistic interactions with the viral or host proteins such as Rev and Staufen1." (PMID 30732620, 2019). "To determine whether the expression of these proteins is modulated during HIV-1 infection, we assessed the levels of UPF1, UPF2 and SMG6 expression in HIV-1-infected primary MDMs using an HIV-1 reporter construct called NL4-3-Bal-IRES-HSA." (PMID 30732620, 2019). "This might also be true for UPF1’s newly characterized role in HIV-1 reverse transcription of the vRNA early in HIV-1 infection, at which stage UPF2 still has no role." (PMID 26492277, 2015).
autism (2 papers, 2016 to 2022). Persistent deficits in social interaction and communication and interaction as well as a markedly restricted repertoire of activity and interest as well as repetitive patterns of behavior. "Four of the Root 66 genes (MAP1LC3B, PDE4B, TCF4 and UPF2) have previously been associated with autism, and 56 either have been shown to interact directly with known autism candidates or have been implicated in other autism-related neurological disorders." (PMID 26731442, 2016). "A second network included 14 Root 66 genes (UPF2 already linked to autism) that have been shown to interact with molecules involved in mechanisms responsible for nervous system inflammation, loss of neurological function and abnormal morphology of the brain." (PMID 26731442, 2016). "UPF3B- and UPF2-related disorders recapitulate many of the phenotypes observed in patients carrying the UBAP2L variant, including mild to severe ID, autism-like behaviors, and seizures." (PMID 35977029, 2022). "Four genes in our candidate list for autism (MAP1LC3B, PDE4B, TCF4 and UPF2) have already been associated with ASD." (PMID 26731442, 2016).
colorectal cancer (2 papers, 2008 to 2023). A primary or metastatic malignant neoplasm that affects the colon or rectum. "Genes implicated in the NMD pathway, such as Upf1, Upf2, Smg1, Smg6, and Smg7, are expressed in higher levels in colorectal cancer (CRCs) with microsatellite stability, and promote tumor growth in xenograft models." (PMID 37888706, 2023). "In contrast, transient silencing of UPF1 and/or UPF2 in MSI and MSS colorectal cancer cells (HCT116, LoVo, Co115, LS174T, SW480, COLO320) did not lead to significant alterations of cell growth and/or death in our hands (data not shown)." (PMID 18612427, 2008).
lung carcinoma (2 papers, 2019 to 2022). "The missense mutation rate of UPF1 or UPF2 was higher in lung cancer." (PMID 35993327, 2022). "Analysis of other cancer types using TCGA has shown a similar selectivity to ovarian cancer; in lung cancer or esophageal cancer, the total amplification rate was lower than that for ovarian cancer, but the missense mutation rate was higher in either UPF1 or UPF2." (PMID 31718065, 2019). "With a relatively loose threshold (p < .2), the genes Dhx16, Upf2, Denr, Notch3, Dyrk2, Sec61a1, Hmmr, and Noa1 were reversed in at least three treatment protocols and most of these genes were reported to be related to COPD or lung cancer." (PMID 35993327, 2022).
anemia (1 paper, 2010). A reduction in the number of red blood cells, the amount of hemoglobin, and/or the volume of packed red blood cells. "The relatively normal fetal liver development of UPF2 null livers is further supported by the lack of anemia in these embryos (data not shown), which would be predicted if the liver experienced gross developmental abnormalities." (PMID 20657840, 2010).
breast carcinoma (1 paper, 2021). "The enhanced expression of the UPF2-encoded regulator of nonsense transcripts 2 protein in the combination treatment group might be advantageous to overcome doxorubicin resistance in breast cancer cells." (PMID 34360606, 2021).
cystic fibrosis (1 paper, 2018). Autosomal recessive disorder caused by pathogenic variants in the CFTR gene (cystic fibrosis transmembrane conductance regulator), which encodes a chloride and bicarbonate channel expressed in epithelial cells, and follow the diagnosis criteria. "Particularly, when some key factors in NMD pathway are inhibited, such as ATP dependent RNA helicase upframeshift 1 (UPF1) and upframeshift 2 (UPF2), a better function of the gene implicated in the pathology of cystic fibrosis was noticed." (PMID 30761300, 2018).
diabetes (1 paper, 2025). "The interaction terms under models with both UPF definitions were significantly and positively associated with the likelihood of having diabetes (OR: 1.379, 95% CI: 1.009 to 1.885 for UPF1, and OR: 2.900, 95% CI: 1.197 to 7.028 for UPF2)." (PMID 40806039, 2025).
female infertility (1 paper, 2019). Diminished or absent ability of a female to achieve conception. "Deletion of Upf2 during oocyte growth results in female infertility due to the production of immature GV oocytes that are not competent to undergo meiotic maturation." (PMID 30617251, 2019).
Hepatic steatosis (1 paper, 2010). Steatosis is a term used to denote lipid accumulation within hepatocytes. "This was accompanied by strong disorganization of the liver tissue and by the induction of hepatic steatosis as evidenced by accumulation of lipids in Upf2 null livers." (PMID 20657840, 2010).
Intellectual disability (1 paper, 2023). "UPF3B mutations cause intellectual disability with impairment of neural stem cell differentiation and reduction in neuronal branching, through a loss of UPF2 interaction leading to NMD abrogation." (PMID 37605642, 2023). "NMD has also an important role in neuronal development as demonstrated by the fact that mutations, as well as copy number variations in UPF2 and UPF3B, lead to intellectual disability and/or neurodevelopmental disorders in humans, including schizophrenia and autism spectrum disorder." (PMID 37605642, 2023).
ovarian carcinoma (1 paper, 2019). A malignant neoplasm originating from the surface ovarian epithelium. "Thus, this ovarian cancer type might be an attractive target for UPF1 drug leads, under conditions in which patients have an UPF1 or UPF2 amplification that stimulates the UPF1-dependent NMD pathway." (PMID 31718065, 2019).
status epilepticus (1 paper, 2017). Status epilepticus is defined as a continuous seizure lasting more than 30 min, or two or more seizures without full recovery of consciousness between any of them. "Western blot analysis revealed an increase in Upf1 and p-Upf1 at 8 and 24 hours and Upf2 at 8 hours after status epilepticus in the model." (PMID 28128343, 2017).
steatosis (1 paper, 2018). Increased lipid within the cytoplasm of cells. "This is consistent with the observation that Upf2 liver-specific deletion leads to liver injury and steatosis." (PMID 29334995, 2018).
tumor (10 papers, 2008 to 2023). "This approach led to a significant reduction of Upf2 and Smg1 expression and the up-regulation of tumor rejection antigens, thereby inhibiting tumor growth in vitro and in vivo." (PMID 26863567, 2016). "NMD-inhibition by siRNA targeting of NMD regulatory genes SMG1 or UPF2 has recently been shown capable of inducing protective in vivo immune responses to tumour cells transfected with an NMD-sensitive target antigen." (PMID 21209843, 2010). "Moreover, AsiC mixtures can be easily created from the assembly of individual AsiCs, and the combination of the four most effective EpCAM-AsiCs (targeting Upf2, Parp1, Cd47, and Mcl1) exerted a better tumor inhibition effect than the individual EpCAM-AsiCs." (PMID 36969696, 2023). "The function of EpCAM-AsiCs in the process of cancer immunity was evaluated in genetically engineered mouse breast cancer models, which indicated that Upf2, Parp1, Cd47, and Mcl1 knockdown by EpCAM-AsiCs obviously inhibited tumor progression and promoted tumor-infiltrating immune cell functions." (PMID 36969696, 2023). "Inhibiting the expression of Upf2, Parp1, and Apex1 promoted tumor neoantigen expression." (PMID 36969696, 2023). "UPF1 and UPF2 were also gene edited in 4T1 and B16/F10 tumor." (PMID 36443756, 2022). "To recapitulate the effect of NMD activity in the outcome of tumor progression, we generated different tumor cell lines with their NMD machinery compromised by blocking key NMD factors -SMG1, UPF1, UPF2- via CRISPR." (PMID 36443756, 2022). "Expression levels for NMD-related factors (UPF1, UPF2, UPF3A, UPF3B, SMG1, SMG2, SMG6, and SMG7) were calculated from microarray-derived datasets of primary tumor samples (n = 40 MSI, n = 48 MSS) and matched normal colon samples (n = 95)." (PMID 30228267, 2018). "Our mouse studies showed that deletion of SMG7 significantly decreased tumor growth of our RMS cells and that SMG7 was dispensable for adult mouse survival, which is in contrast to UPF2, where the conditional knockout of UPF2 in adult mice quickly led to death." (PMID 37349371, 2023). "A negative effect of UPF1 and UPF2 expression on the host's anti-tumor response was observed (P<0.01)." (PMID 18612427, 2008).
cancer (4 papers, 2019 to 2025). A tumor composed of atypical neoplastic, often pleomorphic cells that invade other tissues. "Comparing the influence of cancer-derived mutations over different CLMS sites revealed that variants in the PPIs for UPF2 or SMG1 have significant structural stability effects." (PMID 38542156, 2024). "Most of the cancer mutations emerge in the interaction sites of UPF2 in our cross-linking MS experiments, in particular, the H191S induced stability (kcal/mol) within the structure whereas H191N/F reduced the stability." (PMID 38542156, 2024). "Cancer-derived mutations in SMG7 lack any significant effect over the interaction interface with the SMG1 or UPF2 proteins." (PMID 38542156, 2024). "In cancers such as microsatellite instability (MSI) cancers, NMD has been shown, on the contrary, to be activated through increased expression of certain NMD-factor genes: UPF1, UPF2, SMG1, SMG6, and SMG7." (PMID 35052820, 2022).
infection (4 papers, 2018 to 2025). The state of being infected such as from the introduction of a foreign agent such as serum, vaccine, antigenic substance or organism. "UPF1 expression was significantly higher at 9 than that at 6 h post-infection, while UPF2 was significantly upregulated at 9 h post-infection compared to that at all the previous timepoints." (PMID 36768954, 2023). "We found a significant decrease of DExH-Box Helicase 34 (DHX34), suppressor with morphogenetic effect on genitalia 5 (SMG5), and SMG7 expression at 6 h post-infection, followed by a significant increase of these genes and also UPF1 and UPF2 at 9 h post-infection." (PMID 36768954, 2023). "To test the possibility that MHV mRNAs synthesized early in infection are susceptible to NMD, we inoculated MHV into cells treated with control siRNAs (NMD-competent) or with siRNAs for UPF1 or UPF2 (NMD-deficient) and examined the levels of viral mRNAs at different times p.i.." (PMID 30297408, 2018). "Among proteins detected in our study, the regulator of nonsense transcripts 2 (UPF2, Niben101Scf01035g06018.1), required for nonsense-mediated decay, was also previously found to be involved in stress response in Arabidopsis exposed to wounding and infection by Pseudomonas syringae." (PMID 30340407, 2018). "Our data show that NMD inhibition, either by depletion of the NMD factors UPF1 and UPF2 or by wortmannin treatment, resulted in higher levels of MHV mRNA 1 accumulation, which strongly suggests that newly synthesized MHV mRNA 1 is susceptible to NMD early in infection." (PMID 30297408, 2018). "Prior infection, 293T cells were treated with siRNA against UPF1 or UPF2: the monitoring of p19 by FACS confirmed that the absence of UPF1 provoked the reduction in p19 levels." (PMID 40396490, 2025). "We assessed whether STAU1 expression was affected in SARS-CoV-2 infected Calu3 cells expression and found a peak at 3 h post-infection, thus preceding UPF1 and UPF2 upregulation." (PMID 36768954, 2023).
neurodevelopmental disorder (3 papers, 2022 to 2025). A behavioral and cognitive disorder with onset during the developmental period that involves impaired or aberrant development of intellectual, motor, or social functions. "For instance, loss-of-function mutations in UPF2, UPF3B, SMG8 and SMG9 genes, and CNVs targeting UPF2, UPF3A, SMG6, EIF4A3, RNPS1 and RBM8A genes, have been implicated in a variety of neurodevelopmental disorders, including DD, ID, ADHD and TAR syndrome." (PMID 35327467, 2022).
neurodegenerative disease (1 paper, 2024). A disorder of the central nervous system characterized by gradual and progressive loss of neural tissue and neurologic function. "UPF3BY160D significantly inhibits both the interactions of UPF3B with IRE1α and UPF2, suggesting that the missense mutation of UPF3B loses its suppressive function in IRE1α activation, potentially leading to chronic UPR activation for the development of some neurodegenerative diseases." (PMID 39138189, 2024).
UPF2 also shares sentences with these, for which no sentence is quoted: Azoospermia (1 paper); depression (1); developmental delay (1); esophageal cancer (1); neurological disorders (1); type 2 diabetes (1).